GSTM1 (glutathione S-transferase mu 1)
Diseases named in the same sentence as GSTM1 in open-access papers (continued):
Sharing a sentence is not in itself a finding about the gene and the disease.
glaucoma (10 papers, 2008 to 2023). Increased pressure in the eyeball due to obstruction of the outflow of aqueous humor. "Another pathology that has been associated with GSTM1 polymorphisms is glaucoma, with increased incidence of primary open-angle glaucoma (POAG) in the null variant." (PMID 38068321, 2023). "For the glaucoma type, this meta-analysis included ten, eight, and three studies on the relationship between GSTM1, GSTT1, and GSTP1 polymorphism and risk of POAG (the most common form of glaucoma), respectively." (PMID 23342067, 2013). "In conclusion, this study indicates an association of GSTT1 and GSTM1 polymorphisms to a variable degree with three types of glaucoma." (PMID 18334963, 2008). "The overall results indicate a possible variable association between various GSTT1 and GSTM1 genotypes and glaucoma in this population." (PMID 18334963, 2008). "A recent meta-analysis suggested that there might be a significant association between GSTM1 polymorphisms and increased susceptibility to glaucoma." (PMID 33803434, 2021). "Moreover, it is the first study to identify an increased frequency of association of GSTM1 null genotype and GSTP1Ile/Val or GSTP1Val/Val in patients with glaucoma and the influence of these polymorphisms with severity of the disease." (PMID 21738397, 2011). "Several studies have been conducted in different populations to determine the association of GSTT1 and GSTM1 polymorphisms with primary open-angle glaucoma, but to date only three studies have been reported on pseudo-exfoliative glaucoma (PEXG) in populations of Arabs, Turks and Swedes." (PMID 21151336, 2010). "We found a nominally significant association of GSTM1 gene deletion with decreased risk of ocular hypertension and a protective role of IL1B rs16944 and IL6 rs1800629 in the risk of glaucoma." (PMID 33803434, 2021). "All studies evaluating the association between GSTM1, GSTT1 and GSTP1 polymorphisms and glaucoma risk were included." (PMID 23342067, 2013). "In this study, we have conducted a meta-analysis to assess the association between polymorphisms of GSTM1, GSTT1 and GSTP1 and glaucoma risk." (PMID 23342067, 2013). "In summary, the present meta-analysis suggested that combination of GSTM1 and GSTT1 null genotypes, and GSTM1 null and GSTP1 105-Val allele genotypes are associated with increased risk for glaucoma in Caucasian populations." (PMID 23342067, 2013). "Our meta-analysis results showed that the association between combined of GSTM1 and GSTT1 null genotypes, or GSTM1 null and GSTP1 Val genotypes, and the risk for glaucoma is statistically significant in Caucasians." (PMID 23342067, 2013). "Due to the limited studies, we did not perform meta-analysis for association between the combined GSTM1 null, GSTT1 null and GSTP1 105-Val allele genotypes and glaucoma risk." (PMID 23342067, 2013). "The combination of GSTM1 null and GSTT1 null, or GSTM1 null and GSTP1 genotype was associated with increased risk of glaucoma." (PMID 23342067, 2013). "The GSTM1 and GSTT1 polymorphisms were reported to be associated with many diseases, including glaucoma, acute leukemia, senile macular degeneration, and cataract, in the different populations tested." (PMID 22665971, 2012). "Many factors might account for the differences in results between similar studies, such as differences in sample size, types of glaucoma and ethnic and geographical GSTM1 null and GSTT1 null distribution in populations." (PMID 33803434, 2021). "GSTM1 and GSTT1 gene deletion was extensively investigated with regard to glaucoma risk." (PMID 33803434, 2021). "In addition, we included four and three studies on the association between the GSTM1 and GSTT1 polymorphism and risk of other types of glaucoma (including exfoliative glaucoma and primary closed angle glaucoma), respectively." (PMID 23342067, 2013).
glaucoma (continued). "Interestingly, increased glaucoma risk was associated with the combined GSTM1 and GSTT1 null genotypes (OR, 2.20; 95% CI, 1.47–3.31), and with the combined GSTM1 null and GSTP1 Val genotypes (OR, 1.86; 95% CI, 1.15–3.01)." (PMID 23342067, 2013). "Moreover, the GSTM1 genotype assessed by polymerase chain reaction in DNA samples showed that the GSTM1-null genotype was significantly more common in patients with glaucoma, who also showed significantly higher levels of 8-OHdG as compared with patients with GSTM1-positive genotype." (PMID 33807538, 2021).
head and neck cancer (10 papers, 2006 to 2024). A primary or metastatic malignant neoplasm affecting the head and neck. "Moreover, a study comprising of 2500 individuals demonstrated that environmental risk factors significantly increase susceptibility to head and neck cancer in GSTM1 null individuals." (PMID 39726707, 2024). "GSTT1 and GSTM1 polymorphism studies done in head and neck carcinomas are contradictory." (PMID 17221058, 2006). "Aberrant methylation of GSTM1 has been found in various cancers, such as acute myeloid leukaemia, urothelial carcinoma and head and neck cancer." (PMID 35126454, 2021). "Previous studies have shown that a homozygous deletion or null genotype of the GSTM1 and GSTT1 gene that results in loss of the enzyme’s function and so increases susceptibility to head and neck cancer." (PMID 32882964, 2020). "In another study, the stratified analysis by ethnicity demonstrated significant risks for GSTM1 null genotypes and head and neck cancer among Asians (OR = 1.39, 95% CI = 1.27-1.53; P = 0.000), but not in Caucasians (OR = 0.99, 95% CI = 0.83-1.18; P = 0.677), thus corroborating our results." (PMID 32592358, 2020). "GSTM1 and GSTT1 null genotype results in incapacity to detoxify carcinogens related to tobacco smoke, which can increase the risk of smoking-related cancer, such as lung, bladder cancer and head and neck cancer." (PMID 32882964, 2020). "In a more recent study, GSTM1 but not GSTT1 null genotype was indicated to associate with head and neck cancer risk, in agreement with our study." (PMID 19338664, 2009). "A study by Konig-Greger et al47 showed that GSTM1-enzyme activity was significantly reduced in patients with head and neck carcinoma compared to controls, although it did not depend on the unfavorable GSTM1 genotype, which may suggest that other enzymes participate as regulators." (PMID 17221058, 2006).
type 2 diabetes mellitus (10 papers, 2011 to 2025). A type of diabetes mellitus that is characterized by insulin resistance or desensitization and increased blood glucose levels. "In this research the deletion of two of the most important genes of this family; GSTT1 and GSTM1 genes was investigated as the risk factor for diabetes mellitus type II and one of its most important complications; retinopathy." (PMID 24355557, 2013). "The results indicated that there was significant relationship between GSTM1 null genotype with retinopathy side effect of diabetes type 2." (PMID 24355557, 2013). "The link between polymorphic genes involved in redox homeostasis, such as GCLM (rs2301022), GGT7 (rs6119534, rs11546155), GSTM1 (+/del), GSTP1 (rs1695, rs1138272), RAC1 (rs7784465), and CYBB (rs5917471), and type 2 diabetes differs in overweight and normal-weight individuals." (PMID 36902173, 2023).
acute myeloid leukemia (9 papers, 2016 to 2024). Acute myeloid leukemia (AML) is a group of neoplasms arising from precursor cells committed to the myeloid cell-line differentiation. "For example, Chen and co-authors described that GSTM1 null genotype combined with CYP1A1 and CYP2D6 heterozygous mutant genotypes were correlated with an elevated risk of acute non-lymphoblastic leukemia (ANLL)." (PMID 31681592, 2019). "Another study that included adult patients with Acute Myeloid Leukemia showed the GSTM1 null genotype shortened the disease-free survival; and this association was even stronger when the GSTT1 and GSTM1 null genotypes were combined." (PMID 27058755, 2017). "The purpose of the study was to evaluate the association between CAT C262T, GPX1 Pro198Leu, MnSOD Ala16Val, GSTM1, GSTT1, and GSTP1 Ile105Val gene polymorphisms and acute myeloid leukemia risk, in a case-control study comprising 102 patients and 303 controls." (PMID 26823947, 2016). "In a meta-analysis, it was revealed that, the GSTM1-null genotype, but not GSTP1 Ile105Val polymorphism, was associated with an increased risk of acute myeloid leukemia in East Asians and GSTT1-null genotype in Caucasians." (PMID 29204680, 2018).
colon carcinoma (9 papers, 2007 to 2025). "Specifically, the strongest inverse association between cruciferous vegetable intake and colon cancer risk is observed among younger individuals (particularly those under 55) with the GSTM1-null genotype, and the benefit appears more pronounced in smokers." (PMID 41246347, 2025). "Moreover, the GSTM1 null genotype was also associated with an increased colon cancer risk (OR = 1.32, 95% CI: 1.16–1.51, I2 = 57.7%)." (PMID 32776111, 2020). "Moreover, the GSTM1 null genotype was also associated with an increased colon cancer risk (OR = 1.32, 95% CI: 1.16–1.51)." (PMID 32776111, 2020). "A previous study indicated that GSTM1-3 were significantly decreased in colon cancer tissue samples compared to normal tissues samples." (PMID 35965498, 2022). "Strong associations were also found between smoking and rectal cancer, as well as GSTM1 and GSTT1 polymorphisms with colon cancer." (PMID 17547744, 2007). "In addition, the GSTM1 null genotype was associated with colon cancer risk but not rectal cancer, while conversely that the GSTT1 null genotype was associated with rectal caner but not colon cancer." (PMID 32776111, 2020). "GSTM1, GSTM2, and GSTM3 were expressed at significantly higher levels in normal tissues than in colon tumor tissues." (PMID 32539715, 2020). "Synbiotics intervention increased glutathione‐S‐transferase mu‐1 (GSTM1) and decreased MAPK9 gene expression in colon tumors, thereby attenuating the promotive and progressive effects of indole‐3 carbinol on colon carcinogenesis and reducing the risk of colon cancer in rats." (PMID 37937304, 2023).
epilepsy (9 papers, 2010 to 2024). A brain disorder characterized by episodes of abnormally increased neuronal discharge resulting in transient episodes of sensory or motor neurological dysfunction, or psychic dysfunction. "We have shown that in KM rats, compared with W and “0” rats, there was a decrease in the transcription of the Igfbp5 and Gstm1 genes, the mutations of which were shown to increase the risk of developing epilepsy in humans." (PMID 34803604, 2021). "Carriers of GSTM1-null genotypes in European and Asian populations have been found to show significant risk of developing epilepsy, emphasizing the involvement of the antioxidant system in seizure susceptibility." (PMID 34803604, 2021). "In contrast to our results, a study performed in a Tunisian population recognized carriers of the GSTM1-null genotype to be in a higher risk of epilepsy." (PMID 34248709, 2021). "A retrospective study in Japanese patients with epilepsy implicated the GSTM1 null genotype as a risk factor for carbamazepine-induced mild hepatotoxicity, whereas the EPHX1 polymorphisms did not lead to any elevation of transaminases in 192 Japanese patients treated with carbamazepine." (PMID 27713373, 2010). "Other common genes including MTHFR, GSTM1, CYP17A1, and CACNB2 are implicated in neurological disorders such as epilepsy." (PMID 34899152, 2021). "On the other hand, a study done in an Indian population showed a higher risk of epilepsy in individuals with the GSTT1-null genotype and a lower risk in GSTM1-null carriers." (PMID 34248709, 2021). "In this study both GSTM1 and GSTT1 null genotypes were analysed to evaluate the effects on epilepsy risk susceptibility." (PMID 29362397, 2018). "In a previous case-control study, an association of the GSTM1 null and GSTT1 null genotypes with an increased γ-GT levels was reported in VPA-treated Japanese patients with epilepsy." (PMID 25372290, 2014). "An association between the common polymorphisms in the GSTM1 and GSTT1 null genes and an increase of γ-glutamyltransferase, which was proposed to be a surrogate marker for mild hepatotoxicity in the study, was reported in 149 valproic acid-treated Japanese patients with epilepsy." (PMID 27713373, 2010). "Bioinformatics analysis revealed that the effects of AS3MT on epilepsy likely involved multiple targets including MTHFR, GSTM1, CYP17A1, NT5C2, YBX3, CNNM2, CACNB2, and TRIM26." (PMID 34899152, 2021). "During the model developments, we evaluated the associations of the VPA-induced γ-GT elevation with patient-specific covariates, including the SOD2, GSTM1 and GSTT1 genotypes, in Japanese patients with epilepsy." (PMID 25372290, 2014). "The effects of AS3MT on epilepsy might involve multiple targets including CNNM2, CACNB2, TRIM26, MTHFR, GSTM1, CYP17A1, NT5C2, and YBX3." (PMID 34899152, 2021). "The results obtained revealed that GSTM1 null genotype and not GSTT1 null genotype is significantly associated with epilepsy and possibly involved in the development of the disease." (PMID 29362397, 2018).
male infertility (9 papers, 2015 to 2025). The inability of the male to effect fertilization of an ovum after a specified period of unprotected intercourse. "Our results are in agreement with several studies that reveal GSTM1-null genotype as a potential risk factor for male idiopathic infertility by affecting semen quality." (PMID 37959238, 2023). "Our results demonstrated that the GSTM1-null genotype was present at a higher frequency in infertile men than in the fertile control group, with a 2.22-fold increase for the risk of male infertility." (PMID 37959238, 2023). "The possible relationship of GSTM1 gene deficiency with male infertility has been studied extensively, but the results of the studies vary between different populations." (PMID 37959238, 2023). "Regarding male infertility, we have shown that GSTM1-null variant is associated with a two-fold higher risk for infertility." (PMID 38068321, 2023). "An association has been demonstrated between GSTM1 polymorphism, markers of oxidative stress, and damage in spermatozoa and seminal plasma in subjects with idiopathic male infertility." (PMID 37959238, 2023). "The present case–control study focused on the potential impact of the GSTM1 polymorphism and redox potential on the risk for idiopathic male infertility." (PMID 37959238, 2023). "However, in a recent study, researchers proposed the GSTM1-null genotype as a potential genetic risk factor for male infertility, interfering with certain oxidative stress markers (i.e., total antioxidant capacity and nitric oxide) in infertile men." (PMID 37959238, 2023). "Similarly, a subsequent meta-analysis concluded that the GSTM1-null polymorphism contributes to a significant increased risk for male infertility." (PMID 37959238, 2023). "Moreover, an increased risk for male infertility of GSTM1-null genotype was revealed in a previous meta-analysis." (PMID 37959238, 2023). "Furthermore, our study’s aim is to examine whether testing for GSTM1 polymorphism could be a potential biomarker in male infertility investigation." (PMID 37959238, 2023). "Concerning the link between GST polymorphisms and the urogenital system, some research shown that variations in GSTM1, GSTT1, and GSTP1 are linked to male infertility." (PMID 39063019, 2024). "Further studies are needed to evaluate the combined or independent use of GSTM1 genotyping as a potential biomarker for male infertility assessment." (PMID 37959238, 2023). "Three types of GST SNPs, namely, GSTT1-null, GSTM1-null, and GSTP1 Ile105Val, have been extensively demonstrated to be associated with male infertility in various ethnic populations." (PMID 26618172, 2015). "Meta-analysis further confirmed that GSTM1-null and GSTT1-null polymorphisms are associated with male infertility risk." (PMID 26618172, 2015). "GSTM1- and GSTT1-null genotypes have also been associated with male infertility." (PMID 38068321, 2023). "Another study discovered GSTM1 and GSTT1 null genotype are associated with male infertility." (PMID 33083304, 2020). "Furthermore, a prospective study from North America showed that the MTHFR 677TT homozygous variant was associated with male infertility, but not in a subgroup of patients with a common deletion of Glutathione S-Transferase Mu 1 (GSTM1), a gene encoding glutathione transferase." (PMID 41156464, 2025). "In another study by Salehi and coworkers, the relationship between the combination of GSTM1 and GSTT1 null genotypes and the increasing probability of idiopathic male infertility was emphasized again." (PMID 29766145, 2018). "Numerous population studies have suggested a negative effect of the GSTM1-null genotype on male infertility, with patients carrying the GSTM1-null genotype having a lower sperm concentration and sperm count." (PMID 37959238, 2023).
male infertility (continued). "However, other papers showed that CYP1A1*2A CC and the combination of GSTM1 and CYP1A1*2C genotypes were associated with increased risk of male infertility, while CYP1A1*2A TC genotype showed a non-significant increased risk of male infertility." (PMID 29766145, 2018).
tuberculosis (9 papers, 2012 to 2025). A chronic, recurrent infection caused by the bacterium Mycobacterium tuberculosis. "The glutathione S-transferases (GST) plays a crucial role in the detoxification of hepatotoxic metabolites of anti-tuberculosis drugs.An association between GSTM1/GSTT1 null mutations and increased risk of ATDH has been demonstrated in adults." (PMID 25525805, 2014). "In summary, our meta-analysis indicates that CYP2E1, NAT2 and GSTM1 genetic variation is significantly associated with anti-tuberculosis drug-induced liver injury." (PMID 23082213, 2012). "Given the ethnic differences and developmental changes, our study aims to investigate the potential impacts of GSTM1/GSTT1genotypes on the development of ATDH in Han Chinese children treated with anti-tuberculosis therapy." (PMID 25525805, 2014). "The results did not support the GSTM1 or GSTT1 polymorphisms as risk factors of the development of ADTH in Chinese Han children receiving anti-tuberculosis drug therapy." (PMID 25525805, 2014). "Bothhepatic GSTT1 and GSTT3 can be induced by PPARα inducers such asclofibrate, An associationbetween GSTM1/GSTT1 null mutations and increased risk of anti-tuberculosis drugshas been demonstrated in adults, but not in children." (PMID 30444463, 2018). "Given the ethnic difference in the correlation between the GST genetic polymorphism and ATDH, and apotential impact of age, our study aims to investigate the impacts of the GSTM1 and GSTT1 genotypes on the development of ATDH in Han Chinese children receiving anti-tuberculosis therapy." (PMID 25525805, 2014). "Ourresults did not support the GSTM1 and GSTT1 polymorphisms as the predictors of ADTH in Chinese Han children treated with anti-tuberculosis drugs." (PMID 25525805, 2014).
Alzheimer disease (8 papers, 2013 to 2024). A progressive, neurodegenerative disease characterized by loss of function and death of nerve cells in several areas of the brain leading to loss of cognitive function such as memory and language. "Simon and colleagues showed that 72% of patients carriers of GSTM1(−)/T1(−) alleles have at least three times elevated ALT levels among Alzheimer’s disease." (PMID 29523098, 2018). "They found that the supplementation of short-chain fatty acids can significantly regulate neurotransmitter uptake and upregulate genes involved in astrocyte-neuron metabolic coupling (including Glul, Slc1a2, and Gstm1), thereby improving Alzheimer’s disease symptoms in mice." (PMID 39440247, 2024). "For instance, the GSTP1 Ile105Val polymorphism and GSTM1 null genotype but not the GSTT1 null genotype seem to increase the risk of Alzheimer’s disease." (PMID 30617052, 2019).